IDH1 (isocitrate dehydrogenase (NADP(+)) 1)
Diseases named in the same sentence as IDH1 in open-access papers (continued):
Sharing a sentence is not in itself a finding about the gene and the disease.
astrocytomas (continued). "Differences in growth pattern and growth rate between IDH1-mutated oligodendrogliomas and astrocytomas may variably impact cognitive functions before and after surgery." (PMID 41514682, 2026). "Similarly, hemizygous loss of CDKN2A/B is associated with reduced survival in IDH1/2 mutant astrocytomas." (PMID 40949165, 2025). "Astrocytomas are defined by a mutation in the isocitrate dehydrogenase 1 (IDH1) gene." (PMID 41002991, 2025). "Interestingly, astrocytomas harboring the IDH1 R132H mutation (~90%) display lower genomic methylation compared to non-R132H mutations, which signifies a poorer prognosis." (PMID 41009641, 2025). "Interestingly, in lower-grade astrocytomas with IDH1 mutations, higher GLUD1 and GPT2 expression correlates with lower GSH levels, potentially increasing sensitivity to oxidative stress and treatments like radiation therapy." (PMID 41009025, 2025). "The greater decline among IDH-mutant astrocytomas (6.7 months vs. 1.7 months) suggests that the early protective benefit of IDH1 mutations may diminish over time." (PMID 40261557, 2025). "The patient who carried the R132S mutation was older than 55 years and could not be accurately diagnosed using IHC, highlighting the relevance of using genomic techniques to evaluate IDH1 mutations in astrocytoma patients." (PMID 41044136, 2025). "The United States Food and Drug Administration (FDA) and the Australian Therapeutic Goods Administration (TGA) recently approved one such agent, vorasidenib, for adult and pediatric patients 12 years and older with grade 2 astrocytoma or oligodendroglioma with a susceptible IDH1 or IDH2 mutation." (PMID 39876890, 2024). "IDH1/2 wt astrocytomas, with TERT mutation only, have the highest age of onset (62 years)." (PMID 38326661, 2024). "Moreover, the IDH1(R132H)‐specific peptide vaccine (IDH1‐vac) elicited immune responses in 93.3% of patients diagnosed with WHO grade 3 and 4 IDH1(R132H) + astrocytomas, spanning multiple alleles." (PMID 39215399, 2024). "While the association between mutations in ATRX and IDH1 has been known for over a decade, the details of their interaction and basis for frequent co-occurrence in astrocytomas remains unclear." (PMID 38272925, 2024). "While the association between mutations in ATRX and IDH1 has been known for over a decade, the details of their interaction and basis for recurrent co-occurrence in astrocytoma remains unclear." (PMID 38272925, 2024). "IDH1mt GBMs, strongly associated with neuronal/proneuronal subsets of GBMs, are nowadays classified as a part of spectrum of IDH1mt astrocytomas (Astrocytoma, IDH1-mutated, CNS WHO grade 4); we therefore analysed them in the group with other IDH1mt astrocytomas." (PMID 37568909, 2023). "The gene expression profile of lower-grade astrocytomas (mainly of those harboring the IDH1 mutation) indicated that tumor cells might be sensitized to oxidative stress due to reduced glutathione synthesis." (PMID 36834608, 2023). "However, the use of the anti-IDH1 R132H antibody has its limitations; although most oligodendrogliomas and low-grade astrocytomas carry the IDH1 R132H mutation, other mutations occur in IDH1 or IDH2 genes that cannot be detected with the antibody." (PMID 37568909, 2023). "Among all adult-type diffuse gliomas combined, the optimal driver mutation VAF (either TERT for IDHwt GBM or IDH1/2 for IDHmut astrocytoma and IDHmut oligodendroglioma) in the context of MGMT promoter methylation pyrosequencing was determined by Cutoff Finder at 0.325." (PMID 37919784, 2023).
astrocytomas (continued). "Mutations in CHK2 are instead associated with an IDH1-wildtype astrocytoma." (PMID 35406593, 2022). "The IDH1 mutation was seen in all cases of oligodendrogliomas and in the Grade II–IV astrocytomas." (PMID 36289655, 2022). "Analysis of cell proportions in grades II and III IDH1-mutated astrocytoma tumors (n = 32), using single cell and bulk RNAseq data, revealed no significant changes in the proportions of malignant astrocytes, macrophages, oligodendrocytes, and T-cells within a tumor, between grades II and III." (PMID 36291914, 2022). "In addition, de novo pyrimidine pathway which contributes precursors to DNA synthesis has been recently reported to be a vulnerability of IDH1-mutated astrocytoma." (PMID 36353533, 2022). "In order to distinguish several cell populations in IDH-DGIIG tumors, we examined three diffuse grade II astrocytoma tumors with IDH1 R132H and ATRX mutations and three diffuse grade II oligodendroglioma tumors with an IDH1 R132H mutation and a 1p19q codeletion." (PMID 33925547, 2021). "In contrast, in lower-grade astrocytoma, mainly in those harboring the IDH1 mutation, the gene expression profile indicates that tumor cells might be sensitized to oxidative stress due to reduced GSH synthesis." (PMID 33910646, 2021). "In the present study, we analyzed the expression profile of the genes related to glutaminolysis in different grades of astrocytomas and, more specifically, in the molecular subtypes of GBM, and lower malignant grades of astrocytoma regarding IDH1 mutation status." (PMID 33910646, 2021). "IDH mutated astrocytomas were rare, with one IDH1 and one IDH2 mutated tumor in our cohort." (PMID 34193285, 2021). "The improved outcome of non-R132H IDH1/2-mutated astrocytomas may be explained by a reduced expression of genes that support tumour growth and/or induce treatment sensitivity caused by the increase in CpG methylation." (PMID 33740099, 2021). "Our study showed that 16.5% of astrocytoma harbor IDH1 mutation." (PMID 32856857, 2020). "Our group demonstrated that integrating the values of CHI3L1 and OPN protein expression in serum with IDH1 mutational status into one parameter could predict patient 24-month survival with 86.8% accuracy for astrocytoma patients of all grades." (PMID 33227903, 2020). "Interestingly, IDH2 mutations are mainly found in oligodendrogliomas, while IDH1 mutations differing from R132H are mostly seen in astrocytomas." (PMID 33081358, 2020). "We created an astrocytoma patient survival prediction model consisting of CHI3L1 and OPN expression levels and patient IDH1 mutational status, which predicted two-year astrocytoma patient survival with accuracy rates of 86.8% in all astrocytomas and 93.8% in low-grade astrocytomas (LGG)." (PMID 33227903, 2020). "Our study showed that 16.5% of astrocytomas harbored IDH1 mutation." (PMID 32856857, 2020). "Since IDH1 mutations relate to both astrocytoma and oligodendroglioma, selecting the correct medium is essential to keep the IDH1 mutated model similar to the patient’s condition, because using an inaccurate medium can change the sensitivity of cells to different drugs." (PMID 33221817, 2020). "We demonstrated that integrating serum CHI3L1 and OPN protein level values and tumor isocitrate dehydrogenase 1 IDH1 mutational status into one parameter could predict low-grade astrocytoma patients’ two-year survival with 93.8% accuracy." (PMID 33227903, 2020).
astrocytomas (continued). "However, only in grade II astrocytoma when comparing the PSS’s predicting accuracy with that of individual parameters of PSS (IDH1 mutational status) was a significant improvement demonstrated and 93.8% accuracy reached." (PMID 33227903, 2020). "Also, not all ATRX mutations are associated with loss of nuclear staining, so in a tumor with classic astrocytoma histology and a confirmed IDH1 or IDH2 mutation, positive nuclear staining for ATRX does not exclude the diagnosis of astrocytoma." (PMID 30967140, 2019). "Next, it was evaluated whether astrocytoma with IDH1-mutation (IDH1-mut) could be identified vs. oligodendroglioma." (PMID 31750251, 2019). "Moreover, our results show that there is an association between low HAS2 immunostaining intensity and IDH1 –mutation, which is a known positive prognostic factor in diffusely infiltrating astrocytomas." (PMID 29914429, 2018). "The remaining case was originally classified as a mixed oligo-astrocytoma, which, by virtue of the presence of IDH1_R132 and TERT promoter mutation (C228T), as well as copy-number loss of chromosomes 1p and 19q, would be described as an oligodendroglioma according to WHO 2016." (PMID 29763623, 2018). "IDH1 mutation only cases are astrocytoma with maximal possibility." (PMID 28915860, 2017). "ATRX loss in astrocytomas was also strongly associated with IDH1/2 and H3F3A mutation (p < 0.0001)." (PMID 27311324, 2016). "Our approach to exclusively analyze astrocytomas stratified for IDH1 mutation status from a consecutive LGG database reflects the effort to minimize biological confounders for surgical outcome analysis and clearly distinguishes this series from others published in literature." (PMID 27344556, 2016). "Furthermore, germline variants at 8q24.21 are known to be associated with oligodendroglial tumors and astrocytoma with mutated IDH1 or IDH2." (PMID 26839018, 2016). "However, in oligodendrogliomas, the TERT promoter mutation always occurred in the setting of the IDH1/2 mutation, which is frequent in both oligodendrogliomas and astrocytomas." (PMID 24722048, 2014). "Patients with high-grade astrocytomas with IDH1 mutations were reported to have a better survival." (PMID 23840696, 2013). "Therefore, undiagnosed IDH1/2 wt astrocytomas with TERT mutation only might impact our cohort's tendency towards a higher age of onset." (PMID 38326661, 2024). "Most low-grade scattered astrocytomas (with a 75 percent mutation rate), anaplastic astrocytomas (with a 66 percent mutation rate), oligodendroglioma, promyelocyte, and secondary sex polymorphism include mutations in their IDH1/2 methylation regulatory protein." (PMID 36146527, 2022). "This study indicates that ALT may be the major telomere maintenance mechanism in IDH1 mutation astrocytoma resulting in histidine substitution at arginine 132 (IDH1R132H) mutated astrocytomas and that IDH1R132H downregulates ATRX expression in vitro resulting in ALT." (PMID 33547950, 2021).
astrocytomas (continued). "We searched for differential features of glutaminolysis related to GBM aggressiveness and malignant progression of low-grade astrocytomas with IDH1 mutation, which may help to better characterize the metabolic features associated with GBM aggressiveness and to tumor malignant progression." (PMID 33910646, 2021). "However, the improved outcome of non-R132H IDH1/2-mutated astrocytomas may also be related to the observation that D-2HG is toxic to cells, though only at high concentrations." (PMID 33740099, 2021). "In addition, we examined whether FilGAP, as well as IDH1 mutations, are suitable as prognostic factors and indicators of progression of astrocytomas." (PMID 27790861, 2016). "Based on our data, following histopathology review, tumors classified along the ALGG spectrum including WHO Grades II and III astrocytomas, oligodendrogliomas and mixed tumors could be initially divided based on IDH1/2 mutations into mutant and wildtype groups." (PMID 25257301, 2014). "Particular attention is given to ivosidenib, a selective inhibitor of mutant IDH1, currently evaluated for the treatment of astrocytoma, IDH-mutant, grade 4." (PMID 41599746, 2026). "The aim of the current study was to investigate potential differences in cognitive functioning, particularly focusing on executive functioning, before and up to 1 year after surgery between patients with an IDH1-mutant astrocytoma and oligodendroglioma." (PMID 41514682, 2026). "We report the case of a 31-year-old pregnant woman diagnosed at 24 + 5 weeks of gestation with an IDH1-mutant astrocytoma, WHO Grade 4, harboring a heterozygous CDKN2A/B deletion." (PMID 42294286, 2026). "Adult astrocytomas, particularly IDH1/IDH2-wildtype infiltrating astrocytic gliomas, represent a significant challenge for medical professionals." (PMID 41683621, 2026). "This study examined differences in executive functioning before and up to one year after surgery between patients with IDH1-mutant astrocytoma and oligodendroglioma." (PMID 41514682, 2026). "This study investigated potential differences in the trajectory of performances of executive functioning between patients with IDH1-mutant oligodendroglioma and astrocytoma up to one year after surgery." (PMID 41514682, 2026). "A Phase 1 trial of mesenchymal-derived stem cells loaded with DNX-2401 administered to patients with GBM, IDH-mutant astrocytoma grade 4, gliosarcoma, or wild-type IDH-1 anaplastic astrocytoma is currently ongoing (NCT03896568)." (PMID 40507329, 2025). "The expression level of PKC was notably greater in GBM (grade 4, IDH1‐wildtype), whereas it exhibited comparatively weaker expression in astrocytoma (grade 4, IDH1‐mutant)." (PMID 39716938, 2025). "Compared to histopathologic grade alone, the combination of CDKN2A/B loss, focal amplifications, and histopathologic grade better defined a group of IDH1/2-mutant astrocytoma patients with intermediate overall survival." (PMID 39584448, 2025). "IDH1/2-mutant astrocytomas rarely exhibited EGFR amplifications (3%), which were confined to high-grade tumors." (PMID 41377022, 2025). "VORANIGO (vorasidenib) is an IDH1/IDH2 inhibitor approved by the FDA on 6 August 2024 for adult and pediatric patients 12 years and older with surgically intervened Grade 2 astrocytoma/oligodendroglioma harboring IDH1/IDH2 mutations." (PMID 41304751, 2025). "Patients with astrocytomas who presented with seizures had significantly more mutations in glutamate-related genes, including NMDA (64.3% vs. 20%, p = 0.01) and IDH1 (42.7% vs. 10%, p = 0.04)." (PMID 40718831, 2025).
astrocytomas (continued). "Three tumors (9.1%) harbored IDH1 mutations (R132H) leading to their categorization as grade 4 astrocytoma, IDH-1 mutant in the most current WHO classification scheme." (PMID 41066027, 2025). "CTH was specifically up-regulated in IDH1-mutant astrocytomas to sustain de novo GSH production under cysteine restriction, and CTH inhibition with brain-penetrant propargylglycine impaired tumor growth in vivo." (PMID 41154707, 2025). "Among these, patients with IDH1-mutant astrocytomas had a PFS of 17.5 months initially, which declined to 10.8 months after first recurrence." (PMID 40261557, 2025). "Grade 4 IDH1/2-mutant astrocytomas with intact CDKN2A/B and focal amplifications showed decreased median survival at 55.9 months while grade 4 tumors with loss of CDKN2A/B (hemizygous: 31.9 months, homozygous: 32.5 months) fared the worst." (PMID 39584448, 2025). "The mean age at diagnosis for IDH1-mutant astrocytomas was 46.1 years (95% CI: 39.3–52.9), with a median of 48.0 [IQR: 34.3–56.3]." (PMID 40261557, 2025). "GBM exhibited the highest pathway co-alterations (mean: 2.17 pathways affected; median: 2), followed by IDH1/2-mutant astrocytomas (mean: 1.40; median: 1) and oligodendrogliomas (mean: 0.42; median: 1)." (PMID 41377022, 2025). "This cohort comprised 53 IDH1/2-mutant astrocytomas, 19 histone-mutant tumors, 7 with MAPK pathway alterations (BRAF, NF1), 19 GBM (13 pTERTmt) and 2 OD (1pTERTmt)." (PMID 41422096, 2025). "As we better understand the granularity of IDH1/2-mutant astrocytoma molecular alterations from population-level analyses, it becomes critical to consider the composition of each tumor’s unique molecular signature when counseling and managing these patients." (PMID 39584448, 2025). "As MGMT status was unavailable in 38% of HGG patients and 50% of IDH1-mutant astrocytomas, it was excluded from the primary model." (PMID 40261557, 2025). "A phase I trial combines the glutaminase inhibitor telaglenastat with radiation and TMZ in IDH1‐mutant astrocytomas (NCT03528642)." (PMID 38105543, 2025). "We further observed a cluster of IDH1/2-mutant astrocytoma with oligodendroglioma-like features (group 7)." (PMID 39584448, 2025). "In IDH1/2-mutant astrocytomas, EGFR amplifications were rare (1.7%) but confined to higher-grade tumors (grade 3: 5 tumors, grade 4: 12 tumors)." (PMID 39164213, 2025). "A phase I study (NCT02454634) found that the IDH1-vac vaccine was well-tolerated and produced immune responses in 93.3% of patients with IDH1(R132H)-positive astrocytomas." (PMID 40514725, 2025). "Others have reported that faster progressing mutant IDH1-driven astrocytomas had increased copy numbers in EGFR, MYC, MET, and CDK6 compared to slower-progressing patients." (PMID 40188944, 2025). "Taken together, our findings support the existence of a clinically distinct group of IDH1/2-mutant astrocytoma with an intermediate prognosis, which can guide patient management and trial consideration." (PMID 39584448, 2025). "In pediatric population, the incidence rate of IDH1/2 mutant astrocytoma was 0.09 per 100,000 population with 9.1% tumors histologically low grades (WHO grade 1 and 2) and 9% high grades (WHO grade 3 and 4)." (PMID 40949165, 2025).